SLPI (secretory leukocyte peptidase inhibitor)
Diseases named in the same sentence as SLPI in open-access papers (continued):
Sharing a sentence is not in itself a finding about the gene and the disease.
bacterial vaginosis (4 papers, 2010 to 2023). Infection caused by bacterial overgrowth in the vagina. "Following pathological insult, serine protease inhibitors HE4 and SLPI have an inverse relationship, for example in bacterial vaginosis, HE4 is elevated, whereas SLPI is decreased." (PMID 27379082, 2016). "Another study found that higher levels of secretory leukocyte peptidase inhibitor (SLPI), an antimicrobial peptide that is typically depleted in women with conditions such as bacterial vaginosis, can be observed in women with high levels of Lactobacillus iners." (PMID 37374929, 2023). "We compared vaginal proinflammatory cytokine and secretory leukocyte protease inhibitor (SLPI) concentrations among pregnant and nonpregnant women according to bacterial vaginosis (BV) status." (PMID 21490741, 2010).
colitis (4 papers, 2015 to 2024). Inflammation of the colon. "We previously showed that the protease inhibitory activity of SLPI prevents the intestinal epithelial barrier dysfunction caused by excessive NE activity in DSS-induced colitis." (PMID 39524440, 2024). "Experimental colitis was induced in wild-type (WT) mice and SLPI-deficient (KO) mice by dextran sulfate sodium (DSS) after oral administration of DKT." (PMID 39524440, 2024). "To clarify the role of SLPI in the suppressive effect of DKT on DSS-induced colitis, we next evaluated the effect of DKT on DSS-induced colitis in WT and SLPI-/- mice." (PMID 39524440, 2024). "In mouse models of colitis, the same upregulation of SLPI occurred, promoting recovery from disease through inhibition of neutrophil elastase." (PMID 38736885, 2024). "In conclusion, DKT exerts a protective effect against DSS-induced colitis, in which SLPI promotes prebiotic effects by reshaping the gut microbiota and increasing butyrate-producing bacteria, while enhancing the integrity of the intestinal epithelial barrier through protease inhibitory activity." (PMID 39524440, 2024). "Here, we showed that oral administration of DKT induced the expression of SLPI, in association with an increase in the number of butyric acid-producing bacteria in the colon of mice, and administration of DKT ameliorated the disease severity of DSS-induced colitis in an SLPI-dependent manner." (PMID 39524440, 2024). "We, therefore, explored the possible involvement of DKT and SLPI in the regulation of the gut microbiota composition, and its effect on DSS-induced colitis." (PMID 39524440, 2024). "Oral administration of DKT increased the number of butyrate-producing bacteria, such as Parabacteroides, Allobaculum, and Akkermansia, enhanced the levels of short-chain fatty acids, including butyrate, in the colon, induced SLPI expression, and ameliorated DSS-induced colitis in WT mice." (PMID 39524440, 2024). "Given the protease inhibitory activity of SLPI, it is likely that administration of DKT might inhibit the activity of NE that is enhanced by DSS-induced colitis." (PMID 39524440, 2024). "In this study, we revealed that administration of DKT attenuates DSS-induced colitis in WT mice, but not in SLPI-/- mice." (PMID 39524440, 2024). "In the present study, we showed that SLPI, directly induced by DKT in the colon, as well as indirectly by modulating the gut microbiota and increasing butyrate production, alleviates DSS-induced colitis by protecting the intestinal epithelial barrier." (PMID 39524440, 2024).
cystic fibrosis (4 papers, 2019 to 2025). Autosomal recessive disorder caused by pathogenic variants in the CFTR gene (cystic fibrosis transmembrane conductance regulator), which encodes a chloride and bicarbonate channel expressed in epithelial cells, and follow the diagnosis criteria. "The overexpression of cathepsin G and underexpression of SERPINB1 and SLPI have been reported in muco-obstructive respiratory diseases such as cystic fibrosis and COPD." (PMID 40650225, 2025).
Hyperkeratosis (4 papers, 2014 to 2020). Hyperkeratosis is a histopathological term defining a thickened stratum corneum and may be present in many different skin conditions, with many possible overlaps. "Upregulation of epigen, secretory leukocyte peptidase inhibitor (Slpi), and small proline-rich protein 2d (Sprr2d) in hair follicles was identified as the likely cause of infundibular acanthosis, hyperkeratosis, and cyst formation." (PMID 24503019, 2014). "Finally, secretory leukocyte peptidase inhibitor (SLPI) mediates hyperkeratosis." (PMID 31485292, 2019).
lung fibrosis (4 papers, 2020 to 2023). "SLPI deficiency does not affect bleomycin-induced lung fibrosis development in mice." (PMID 35840034, 2022). "The absence of secretory leukocyte protease inhibitor (SLPI), a host protein implicated in IPF, leads to the impairment of collagen gene expression in a mouse model of bleomycin-induced lung fibrosis." (PMID 33043031, 2020). "Furthermore, we show that DZNep treatment alone or in context of SARS‐CoV or SARS‐CoV‐2 infections reduces abundance of pulmonary fibrosis markers (e.g., SERPINE1, MMP14, and COL4A1) and increases levels of factors with antifibrotic activity (e.g., HOPX, PI3/ELAFIN, and SLPI)." (PMID 35833542, 2022).
Arthritis (3 papers, 2018 to 2025). Inflammation of a joint. "Moreover, SLPI has been associated with susceptibility factors in conditions like necrotizing fasciitis and arthritis, reinforcing its role in tissue integrity and immune defense." (PMID 40723781, 2025). "Recombinant SLPI (rSLPI) has been explored in preclinical models of arthritis, where intra-articular administration attenuates cartilage erosion and reduces inflammatory cytokine production." (PMID 40723781, 2025). "SLPI protects epithelial tissue from serine proteases, and reportedly reduces inflammation and joint damage in arthritis." (PMID 30034392, 2018). "SLPI might suppress MMP-3 and MMP-13 expression in chondrocytes under IL-1β, and it might be linked to reduced MMP in arthritis models." (PMID 40723781, 2025). "Interestingly, acetylation-dependent GR increases the transcription of SLPI, which suppresses inflammation and joint damage in arthritis by downregulating TNF-α." (PMID 30034392, 2018). "As C57BL/6 mice only develop mild arthritis, if any, after challenge with B. burgdorferi, this mouse provided an ideal example to study whether the lack of SLPI could cause an arthritis-resistant mouse to become arthritis-susceptible." (PMID 40392222, 2025). "Similar to our data from B. burgdorferi-infected mice, this result suggests a correlation between the lack of SLPI and humans exhibiting clinical manifestations of Lyme disease, including arthritis." (PMID 40392222, 2025).
atherosclerosis (3 papers, 2020 to 2024). A disease characterized by the build-up of fatty material and calcium deposition in the arterial wall resulting in partial or complete occlusion of the arterial lumen. "On the other hand, protective roles of SLPI have been demonstrated against progression of atherosclerosis (Zhong, Wang, Li, Peng, & Jiang, 2017)." (PMID 32157804, 2020). "The inflammatory suppression role of SLPI may confer protection against atherosclerosis by neutralizing the effect of inflammatory factors such as TNF-α or by blocking the activation of NF-κB." (PMID 36299596, 2022).
cervical cancer (3 papers, 2012 to 2021). A primary or metastatic malignant neoplasm involving the cervix. "In the context of our results demonstrating that SLPI may play a role in HPV16 infection by inhibiting entry into epithelial cells, the evidence showing that HSV down-regulates SLPI may explain the epidemiological association between HSV and HPV induced cervical cancer." (PMID 22927980, 2012). "These genes, particularly CEBPD, SLPI, KRT16, and NOTCH1, may serve as potential biomarkers at the mRNA level for the course of cervical cancer development, and warrant further study as it relates to understanding HPV-dependent carcinogenesis." (PMID 34944802, 2021). "It has been reported that SLPI is upregulated in non-small cell lung cancer (NSCLC), and cancers of the cervix, ovary, and pancreas, but not in those of the kidney, intestinal tract, breast, or nasopharynx." (PMID 32742768, 2020).
COVID-19 (3 papers, 2022 to 2024). A disease caused by infection with severe acute respiratory syndrome coronavirus 2. "In conclusion, we show hyperinflammation characterized by significantly increased cytokine and chemokine levels, hyperactivated neutrophils, and elevated levels of protease inhibitors TIMP-1, SLPI, and elafin in the lungs of critically ill COVID-19 patients in comparison with influenza patients." (PMID 34793331, 2022). "This work identified specific overexpressed genes related to neutrophils only in severe COVID-19 patients, such as SPI1, SLPI, S100A9, and BRI3, which indicates a specific expression regulation that occurs only in SARS-CoV-2 infection." (PMID 38262689, 2024). "Moreover, highly elevated levels of the locally produced serine protease inhibitors secretory leukocyte protease inhibitor (SLPI) and elafin were found in the BAL fluid of COVID-19 in comparison with influenza patients." (PMID 34793331, 2022). "In addition, we detected 100- to 1000-fold higher levels of SLPI and elafin in the BAL fluid of COVID-19 in comparison with influenza patients." (PMID 34793331, 2022). "In addition, significantly increased BAL fluid levels of the protease inhibitors SLPI and elafin were found during the mid/late phase compared with the acute phase of the coinfection in patients with COVID-19 (but not with influenza)." (PMID 34793331, 2022).
eosinophilia (3 papers, 2011 to 2025). "High levels of SLPI were also detected in blood eosinophils from patients with allergy-associated diseases marked by eosinophilia." (PMID 35095834, 2021). "The results showed that SLPI-deficient mice exhibited airway eosinophilia, hyperplasia of goblet cells and high plasmatic IgE levels and decreased resistance of the lungs to allergens, when compared with wild-type mice." (PMID 21887281, 2011). "Both healthy individuals and patients with eosinophilia were uniformly found to contain SLPI-positive circulating eosinophils." (PMID 35095834, 2021). "In contrast to SLPI KO mice treated with the control solvent, BPTI-treated SLPI KO mice showed reduced airway inflammation, fewer total BAL cells, and lower ratios of eosinophilia and Th2 cytokines, including IL-5 and IL-13, in BAL fluid." (PMID 40546642, 2025). "Together, these data suggest that SLPI-upregulated levels in the blood of EGPA and AD patients can be potentially traced to eosinophilia." (PMID 35095834, 2021). "Furthermore, assessment of the ratio of eosinophilia in BAL cells and levels of Th2-type cytokines, including IL-5 and IL-13 in BAL fluid, showed a more marked increase in SLPI KO mice than in WT mice." (PMID 40546642, 2025). "In contrast to mice treated with the control IgG antibody to SLPI KO mice, SLPI KO mice treated with anti-IL-33 neutralizing antibody showed reduced airway inflammation and fewer numbers of BAL total cells, ratio of eosinophilia, and Th2 cytokines (e.g., IL-5 and IL-13) in BAL fluid." (PMID 40546642, 2025).
inflammatory bowel disease (3 papers, 2016 to 2025). A spectrum of small and large bowel inflammatory diseases of unknown etiology. "We investigated the expression of SLPI and the response to quercetin treatment in human inflammatory bowel disease." (PMID 27716626, 2016). "Similarly, in inflammatory bowel disease (IBD), SLPI expression is induced in the intestinal mucosa, where it mitigates protease-mediated injury and promotes mucosal healing." (PMID 40723781, 2025). "Additionally, TSLP also contributes to anti‐apoptotic effects on intestinal epithelial cells in both humans and mice through induction of an endogenous inhibitor, secretory leukocyte peptidase inhibitor (SLPI), for neutrophil elastase that contributes to inflammatory bowel diseases." (PMID 39654685, 2024).
liver cancer (3 papers, 2019 to 2025). An epithelial or non-epithelial malignant neoplasm that arises from the liver. "Moreover, we need to further clarify whether MAPK signaling pathway is a necessary condition for SLPI-induced ER stress and apoptosis of liver cancer cells." (PMID 34975323, 2022). "Secretory leukocyte peptidase inhibitor (SLPI) is upregulated in several cancer types and is highly expressed in liver cancer cell lines." (PMID 40051627, 2025).
oral cancer (3 papers, 2014 to 2023). "Extending these findings, our results suggest a systemic decrease in SLPI, at least in oral epithelial cells, in patients susceptible to oral cancer development." (PMID 24748380, 2014). "Collectively, our results show for the first time a progressive loss of SLPI abundance in the transition from OPML to OSCC, and suggest a novel role for SLPI as a mechanism-linked, non-invasive biomarker of oral cancer, with potential as an OPML treatment agent." (PMID 24748380, 2014). "Our results demonstrating that SLPI inhibits NF-κB transcriptional activity in-vitro in OPML cells further supports its mechanistic role in oral cancer progression." (PMID 24748380, 2014). "SLPI’s role in oral cancer progression is less known, however, recent results in biopsied tissue slices demonstrated a decrease in SLPI in OSCC tissues compared to healthy, as well as a potential role in inhibiting invasiveness." (PMID 24748380, 2014). "Recent findings using in-vitro cell culture have suggested that SLPI inhibits the invasiveness of oral cancer cells." (PMID 24748380, 2014). "Based on these findings, and the known role of SLPI as a protease inhibitor with connections to oral cancer, we chose to further validate and investigate this protein." (PMID 24748380, 2014). "Our study is the first to show SLPI as an inhibitor of NF-κB in the context of oral cancer, specifically in a model OPML cell line." (PMID 24748380, 2014). "Collectively, our results show for the first time the potential for SLPI as a mechanism-based, non-invasive biomarker of oral cancer progression with potential in preventive treatment." (PMID 24748380, 2014). "Among a number of replicated proteins showing abundance differences, the secretory leukocyte protease inhibitor (SLPI) protein showed dramatic decrease relative to normal tissues correlated with the steps of oral cancer progression." (PMID 24748380, 2014). "Our study has revealed several new findings about SLPI’s possible role in oral cancer." (PMID 24748380, 2014). "Our results also suggest a mechanistic role for SLPI in oral cancer progression." (PMID 24748380, 2014). "The findings we present here provide a starting point for such future investigations, which could solidify SLPI as a highly valuable protein in the diagnosis, prognosis and treatment of oral cancer." (PMID 24748380, 2014). "Evidence exists showing that SLPI inhibits NF-κB, although this has not been demonstrated in models of oral cancer." (PMID 24748380, 2014).
pancreatic cancer (3 papers, 2015 to 2022). "In the present study, we investigate the effects of SLPI gene knockdown on the biological behavior of human pancreatic cancer cells." (PMID 25954138, 2015).
pancreatic ductal adenocarcinoma (3 papers, 2015 to 2023). An infiltrating adenocarcinoma that arises from the epithelial cells of the pancreas. "We previously demonstrated that silencing of SLPI through siRNA promoted cell apoptosis and stopped the progression and invasion of pancreatic ductal adenocarcinoma cells." (PMID 36595102, 2023).
periodontitis (3 papers, 2017 to 2024). An acute or chronic inflammatory process that affects the tissues that surround and support the teeth. "In the current study, decreased salivary SLPI levels in patients with periodontitis might be associated with increased NF-κB pathway activation and proinflammatory cytokine expression through the cleavage of this inhibitor." (PMID 36481656, 2022). "Increased levels of neutrophile proteases (elastase, protease 3 and cathepsin B) can contribute to significant depletion of SLPI in the infected periodontitis sites in those patients." (PMID 36481656, 2022). "The present cross-sectional study is the first to investigate the involvement of SLPI in generalized stage 3 grade C periodontitis demonstrating that SLPI levels are reduced in periodontitis, compared with health or gingivitis." (PMID 36481656, 2022). "Additionally, it has been revealed that the levels of the Secretory leukocyte protease inhibitor (SLPI), which has broad-spectrum antimicrobial activity, increases significantly during gingivitis and periodontitis." (PMID 39204254, 2024). "Contrary to Minami31, it has been suggested that reduced SLPI levels were found in GCF and gingival tissue of chronic periodontitis patients infected with P. gingivalis." (PMID 36481656, 2022). "We propose that SLPI represents a novel mechanism that governs the immune cell-like properties of PDL cells, which may be of importance in the pathogenesis of periodontitis." (PMID 28597116, 2017).
sarcopenia (3 papers, 2022 to 2025). Progressive decline in muscle mass due to aging which results in decreased functional capacity of muscles. "Therefore, the high gene expression of SLPI in the sarcopenia group might indicate the importance of inflammation in the pathogenesis of sarcopenia." (PMID 36147639, 2022). "Among them, the expression levels of SLPI and MYH8 in the sarcopenia group were significantly higher than those in the normal group (log2 FC > 1)." (PMID 36147639, 2022). "Notably, the expression levels of SLPI and MYH8 in the sarcopenia group were significantly higher than those in the normal group (log2 FC > 1)." (PMID 36050999, 2022).
triple-negative breast carcinoma (3 papers, 2017 to 2024). An invasive breast carcinoma which is negative for expression of estrogen receptor (ER), progesterone receptor (PR), and human epidermal growth factor receptor 2 (HER2). "Additionally, SLPI represents a potential target for inhibiting metastasis in triple-negative breast cancers." (PMID 38589404, 2024).
atopic dermatitis (2 papers, 2021 to 2025). "These include individuals with eosinophilic granulomatosis with polyangiitis (EGPA) and atopic dermatitis (AD), who were also found to have elevated SLPI levels in their plasma." (PMID 35095834, 2021).
autoimmune disease (2 papers, 2009 to 2022). A disorder resulting from loss of function or tissue destruction of an organ or multiple organs, arising from humoral or cellular immune responses of the individual to their own tissue constituents. "As an increasing body of evidence suggested that MPs have potent proinflammatory activities and are potentially important mediators of inflammatory and autoimmune diseases, we have investigated in this study the role of MPs on BAFF, TSLP, and SLPI secretion by FLSs isolated from RA patients." (PMID 19291304, 2009).
bronchiectasis (2 papers, 2013 to 2018). Segmental, irreversible dilation of the bronchial tree resulting in the accumulation of secretions which leads to obstruction. "To search for additional cleavage fragments, we next loaded a high amount of protein (600 μg) and were able to retrieve an additional cleavage band (cSLPI2), showing that SLPI is indeed cleaved in the airways of bronchiectasis patients and that cleavage fragments can be found." (PMID 29892293, 2018).
diabetes (2 papers, 2021 to 2023). "Consistent with this paradigm, we found that serum SLPI levels are positively correlated with multiple HFpEF comorbidities, including hypertension, diabetes, renal insufficiency, smoking, and dyslipidemia." (PMID 36635319, 2023).